USP9X (ubiquitin specific peptidase 9 X-linked)
Diseases named in the same sentence as USP9X in open-access papers (continued):
Sharing a sentence is not in itself a finding about the gene and the disease.
tumor (continued). "Interestingly, USP9x has been reported to have tumor-promoting activity, acting via stabilization of the pro-survival protein MCL1 in hematological tumors." (PMID 27462448, 2016). "Currently, the role of USP9X in tumor development in the literature is ambiguous." (PMID 27517496, 2016). "Although tumor cells harbored high levels of Mcl-1 and low levels of Beclin 1 – a relationship inversely found in normal cells – a more detailed understanding of how Usp9X regulates both apoptosis and autophagy is necessary." (PMID 26008975, 2015). "USP9X has been found to regulate the stability of a diversity of proteins, and potentially as a result of this appears quite context-dependent in its function, sometimes with oncogenic characteristics and sometimes tumour suppressive." (PMID 26506417, 2015). "In addition, the blocking of USP9X activities using a small-molecule inhibitor decreases Mcl-1 expression by promoting its degradation and thus sensitizes tumor cells to chemotherapeutic agents." (PMID 23171055, 2012). "Together, these evidences indicate that hypoxic tumor microenvironment of OC may be the underlying driver for TGF-β secretion and TGF-β signaling activation, which, in turn, leads to highly expressed USP9X, stabilized HIF-2α and activated CSCs." (PMID 40246814, 2025). "Therefore, USP9X may play an important role in inhibiting or promoting many aspects of a tumor's executive cell signaling pathway and lymphatic metastasis." (PMID 37057289, 2023). "Thus, enforced expression of USP9X enhances tumor growth in vitro and in vivo." (PMID 35884430, 2022). "Therefore, the regulatory role of USP9X in tumor is diverse." (PMID 34112167, 2021). "Therefore, USP9X exerts its tumor inhibitory effect through EGLN3." (PMID 34112167, 2021). "Thus, we identify a tumor suppressor mechanism in the mammalian intestine that arises from the posttranslational regulation of FBW7 by USP9X independent of somatic FBW7 mutations." (PMID 29346117, 2018). "Importantly, the tumor formation of USP9X‐knockdown OSCC cells is significantly decreased." (PMID 29992764, 2018). "Current speculation implicates USP9X as both an oncogene and tumor suppressor." (PMID 27517496, 2016). "Therefore, Usp9X was claimed to exert tumor-suppressive functions." (PMID 26872380, 2016). "Therefore, we envision that USP9X may be a novel tumor marker, a prospective prognostic indicator and a potential therapeutic target for ESCC." (PMID 24152793, 2013). "Fourth, KIFC2 exerted its tumor-promoting and therapy-resistant functions in HR+/HER2– BC by recruiting USP9X to stabilize CDK4." (PMID 40299549, 2025). "We next assessed protein expression levels of KIFC2, USP9X, and CDK4 in 45 tumor samples from patients with HR+/HER2– BC by IHC." (PMID 40299549, 2025). "On the oncogenic side, USP9X stabilizes critical anti-apoptotic proteins (such as MCL-1 and XIAP) through deubiquitination, thereby enhancing tumor cell survival and contributing to chemotherapy resistance, a mechanism observed in multiple malignancies." (PMID 41301681, 2025). "Similar as USP9X, HIF-2α abundance was increased with tumor progression, that is malignant > borderline > benign, and HIF-2α preferred to be distributed in the area of papillary or stratifying structure far from vascular vessels." (PMID 40246814, 2025). "In this study, the authors uncovered that USP9X enhances EGLN3 protein stability via deubiquitination, thereby reinforcing its tumor-suppressive effects." (PMID 41301681, 2025). "Herein, we define the hypoxic tumor microenvironment as the chief stimulator of autocrined TGF-β signaling, which further promotes CSCs occurrence through USP9X-HIF-2α proteostatic regulation." (PMID 40246814, 2025). "Loss of ARID1A led to increased levels of H3K9 and H3K27 acetylation at the USP9X promoter, upregulating the expression of USP9X and PRKAA2, which mediated the adaptation of tumour cells to glucose starvation." (PMID 39471843, 2024).
tumor (continued). "USP9X antagonizes the ubiquitination of FBW7, and its deletion leads to the destabilization of FBW7, resulting in increased levels of c‐MYC and enhanced tumor proliferation." (PMID 39678489, 2024). "Next, USP9X was found to be expressed at high levels in EGR-positive prostate cancer and the USP9X inhibitor WP1130 was found to induce ERG degradation and thus inhibit tumor growth." (PMID 37554324, 2023). "Deubiquitinases USP9X, Ku70, JOSD1, DUB3/USP17L2, and USP13 have been described to stabilize Mcl-1, promote tumor cell survival and suppress apoptosis." (PMID 35301297, 2022). "USP9X has been reported to simultaneously regulate endocytosis of the EGFR by deubiquitinating its endocytic adaptor Eps15 and ubiquitin ligase Itch in tumor cell lines." (PMID 35389885, 2022). "Immunohistochemical analysis of NSCLC specimens showed that the protein expression levels of USP9X and TTK were significantly increased in tumor tissues." (PMID 35784389, 2022). "Exogenous overexpression of Usp9x in SK-Mel29 cells lead to upregulation of SOX2 and as expected, increased 3D tumor growth." (PMID 33613844, 2021). "In order to test our proteomics observations in a larger cohort of patient samples, we analyzed the expression of HUWE1, USP9X and USP7 in protein lysates isolated from fresh frozen PTC patient samples (7 normal, 8 tumor, 3 metastatic lesions)." (PMID 32345963, 2020). "Our data show that expression of HUWE1, USP9X and USP7 are higher in the tumor and metastatic lesions of many patients, compared to matched normal tissue irrespective of their mutational status." (PMID 32345963, 2020). "Quantitative proteomic analysis reveals the upregulation of E3 Ubiquitin ligase HUWE1 and DUBs like USP9X and UBP7 in both tumor and metastatic lesions, which is further confirmed in additional patients." (PMID 32345963, 2020). "Recently, USP9X was reported to be a DUB for YAP deubiquitination, and promote tumor cell survival and chemoresistance." (PMID 31795326, 2019). "Usp9x, Ets-1 and NRAS protein expression was further assessed in a tissue microarray containing tumour and normal tissue." (PMID 28198367, 2017). "Previous studies have suggested that deubiquitinase USP9X stabilizes myeloid cell leukemia sequence 1 (MCL1) and promotes tumor cell survival and apoptosis resistance." (PMID 27783990, 2016). "USP9X depletion increases poly-ubiquitylation of MCL1, enhances its turnover and sensitises tumour cell lines to the pro-apoptotic drug ABT-737 (a BCL2 antagonist that does not target MCL1)." (PMID 25672900, 2015). "Interfering with Usp9X function by chemical inhibition through the deubiquitinase inhibitor, WP1130, results in proteasomal degradation of ERG and impaired growth of tumor cells exhibiting this genetic alteration in vivo." (PMID 26008975, 2015). "We conducted extensive structure-activity relationship studies on WP1130, a Usp5/Usp9x/Usp14/UCH-L1/UCH-L5 inhibitor, to improve its safety, solubility and anti-tumor activity in mice." (PMID 24980819, 2014). "We have shown previously that USP9X inhibition by WP1130 reduces MCL-1 levels, promotes apoptosis and increases tumor cell sensitivity to chemotherapy." (PMID 25606592, 2014). "Our study provides evidence that miR-26b acts as tumor suppressor in HCC, and is an important negative regulator of USP9X." (PMID 24890815, 2014). "In conclusion, we have identified miR-26b as a tumor suppressive miRNA in human HCC, which acts at least in part through the repression of USP9X." (PMID 24890815, 2014). "We additionally found that the USP9X inhibitor WP1130 promotes Mcl-1 degradation and increases tumor cell sensitivity to chemotherapies." (PMID 23171055, 2012). "In seven cases (UCHL1, USP9X, USP11, USP10, USP22, COPS5 and COPS6), dysregulation was observed in more than one tumor type." (PMID 21283576, 2011).
tumor (continued). "The current study demonstrates the key oncogenic role of USP9X that coordinates hypoxia and TGF-β signaling in promoting HGSOC CSCs function, and provides a promising strategy to meliorate tumor relapse, metastasis, chemoresistance, and other tough clinical problems of HGSOC." (PMID 40246814, 2025). "Based on the direct regulation of USP9X on HIF-2α stability, as well as the crucial role of HIF-2α in coordinating hypoxic tumor microenvironment and CSCs maintenance, we hypothesized that USP9X might enhance CSCs occurrence through maintaining HIF-2α." (PMID 40246814, 2025). "Because USP9X affects cell migration and angiogenesis by elevating CCND1-mediated SOX11 expression, USP9X suppression leads to the downregulation of USP9X protein levels in Z-138 and Jeko-1 cell lines and inhibits tumor development in mice in vivo." (PMID 39664521, 2024). "In addition, USP8, USP15, USP9X, and USP18 can directly bind to PD-L1, stabilizing PD-L1 expression and promoting immune evasion by tumor cells." (PMID 39315102, 2024). "USP9X is able to suppress tumor proliferation and EMT by activating the Hippo pathway by deubiquitinating and increasing the stability of LATS, and miR-212 downregulates USP9X by attaching to its 3′UTR." (PMID 38174069, 2023). "In addition, deubiquitinases like USP9X and UBP7 are also highly expressed in both tumor and LN metastatic lesions of the patient with TFG-RET fusion-expressing tumor tissue." (PMID 32345963, 2020). "Finally, the Usp9X pharmacological inhibitor WP1130 significantly reduced human MPNST growth and induced tumor cell death in an in vivo xenograft model." (PMID 30478285, 2018). "While the E3 ligase complexes SCFβ-TRCP and SCFFBXW7 have been shown to ubiquitinate YAP leading to its degradation, USP9X, the only reported YAP DUB, was recently shown to promote tumor cell survival and chemoresistance through deubiquitination and stabilization of YAP50." (PMID 29891922, 2018). "However, other studies have revealed that USP9X deubiquitinates and stabilizes LATS to suppress tumor growth." (PMID 29891922, 2018). "Equally attractive, Usp9x inhibition may be an effective means of targeting NRAS-mutant and -dependent tumours, a goal that has been particularly elusive with other approaches." (PMID 28198367, 2017). "Control and Usp9x-overexpressing SK-Mel29 cells were transplanted into NSG mice, and tumour growth was monitored in control and G9-treated mice (15 mg kg−1, ip, QOD; begun after tumour was measurable)." (PMID 28198367, 2017). "In our report, we confirm earlier observations made in other tumor entities showing that Usp9X levels are up-regulated in tumor tissue but not normal tissue." (PMID 26872380, 2016). "However, how the deubiquitinases (CSN5, USP9X, USP21, OTUB1, and USP22) coordinatePD-L1 protein level in response to distinct tumor microenvironment signals remains unknown." (PMID 34741014, 2021). "Thus, USP9X is a crucial regulator of FBW7 protein levels and function, and the degradation of FBW7 in the absence of USP9X is a mechanism of tumor promotion." (PMID 29346117, 2018). "When comparing USP9X status with clinicopathological variables, we found no significant positive correlations between USP9X expression and age, gender, KPS, histology, tumor size, surgery, radiotherapy and chemotherapy." (PMID 27783990, 2016). "USP9X can also modulate ubiquitin ligase SMURF1, a negative regulator of TGFβ/BMP signaling that controls tumor cell migration and invasion by targeting Rho family proteins." (PMID 25606592, 2014). "They used USP9X knockdown in combination with ABT-737, a small molecule antagonist of the pro-survival proteins not including MCL1 to test increased apoptosis in tumor cells." (PMID 24152793, 2013).
neurodevelopmental disorder (14 papers, 2013 to 2026). A behavioral and cognitive disorder with onset during the developmental period that involves impaired or aberrant development of intellectual, motor, or social functions. "Female-restricted X-linked syndromic intellectual developmental disorder-99 is an ultrarare neurodevelopmental disorder linked to X, manifesting in female individuals due to mutations in the USP9X gene." (PMID 40751225, 2025). "Alterations in USP9X gene in female individuals are associated with neurodevelopmental disorders, hypoplastic corpus callosum, congenital malformations, and dysmorphic facial features." (PMID 40751225, 2025). "Variants in ANK, encoding for ankyrin-G are associated with neurodevelopmental disorders and USP9X patient mutations were shown to reduce interaction with ankyrin-G, strongly suggesting that abnormal ankyrin-G degradation is a pathogenic mechanism in MRX99." (PMID 33335288, 2021). "Four of the identified genes (CUL4B, HDAC8, MED12, and USP9X) have been previously reported to harbor de novo PTVs and Dmis variants in male cases with neurodevelopmental disorders, providing more genetic evidence of their pathogenicity." (PMID 33023636, 2020). "Consistent with its functions during mouse embryonic brain development, USP9X has been implicated in a number of human neurodevelopmental disorders." (PMID 25672900, 2015). "Moreover, the dysregulation of USP9X expression is associated with various neurodevelopmental disorders and neurodegenerative diseases." (PMID 40586131, 2025). "Aggregate phenotypic information of 35 currently known females with predicted pathogenic variation in USP9X reaffirms the clinically recognisable USP9X-female syndrome, and highlights major differences when compared to USP9X-male associated neurodevelopmental disorders." (PMID 33298948, 2020). "Loss or compromised function of USP9X leads to neurodevelopmental disorders in males and females." (PMID 33298948, 2020). "In humans, mutations in USP9X are associated with neurodevelopmental disorders." (PMID 28341829, 2017). "The implications of these data may also extend to humans, where mutations in USP9X are associated with neurodevelopmental disorders." (PMID 27181636, 2016). "Prior studies revealed that lost or compromised function of USP9X leads to neurodevelopmental disorders in humans." (PMID 39974971, 2025). "Recent studies have shown that abnormal expression of USP9X is closely related to a variety of neurodegenerative diseases and neurodevelopmental disorders." (PMID 40586131, 2025). "Additional indirect evidence for the involvement of USP9X in neurodevelopmental disorders comes from its interaction with doublecortin (DCX)." (PMID 25672900, 2015). "With the advance in high throughput genetic sequencing technologies, enquiries into patients with various neurodevelopmental disorders may provide further evidence of the involvement of USP9X." (PMID 25672900, 2015).
neurodegenerative disease (7 papers, 2013 to 2025). A disorder of the central nervous system characterized by gradual and progressive loss of neural tissue and neurologic function. "Given the association of Usp9x overactivation with tumorigenesis and neurodegenerative diseases, we hypothesize that disruption of Xist-mediated XCI may increase female susceptibility to certain diseases." (PMID 40042815, 2025). "Several lines of evidence suggest that USP9X also plays a significant role in the aetiology of neurodegenerative diseases." (PMID 25672900, 2015). "Thus, it will be interesting to investigate further the role of USP9X in neurodegenerative diseases characterised by protein accumulation." (PMID 25672900, 2015).
hematological malignancies (4 papers, 2020 to 2025). "Indeed, USP9X is involved in the regulation of various mitotic and apoptotic proteins and its overexpression is associated with various hematological malignancies, making USP9X a potential theurapeutic target." (PMID 32354135, 2020). "Two different studies reported the positive effect of USP9X targeting in hematological malignancies." (PMID 32674429, 2020). "It has been shown that USP9X positively regulates the protein stability of induced myeloid leukemia cell differentiation protein (MCL1), a BCR-ABL dependent target implicated in drug resistance and cell survival of hematopoietic diseases." (PMID 32674429, 2020). "Inhibition or knockdown of USP9X may therefore be a therapeutic target in various hematological malignancies with abnormal USP9X activity." (PMID 32354135, 2020). "In recent years, some DUBs, such as USP7, USP9X and USP10, have been identified as promising therapeutic targets in hematological malignancies." (PMID 34454635, 2021).
neurological diseases (4 papers, 2015 to 2022). "The complex and dynamic expression of USP9X and its substrates suggests that this task will be a daunting one, but investigations of the effects of rare genetic variants associated with neurological disorders have begun to provide important insights and should remain a focus of future research." (PMID 25672900, 2015).
infection (2 papers, 2013 to 2022). The state of being infected such as from the introduction of a foreign agent such as serum, vaccine, antigenic substance or organism. "USP9x knockout enhanced viral DNA replication at late time points (24 and 72 hrs) post infection, and significantly increased viral titers." (PMID 35709296, 2022). "Moreover, similar to DAOY cells, there were minimal effects during the first 3 days after infection with the USP9X shRNA lentiviral vectors." (PMID 23667531, 2013). "USP9x and RANBP2 immunoprecipitations in HAdV-C5 infection each pulled down pIIIa." (PMID 35709296, 2022).
nervous system tumors (2 papers, 2018 to 2020). "In this study, we found that interference with Usp9X, a deubiquitinating enzyme which is overexpressed in nervous system tumors, or Mcl-1, an anti-apoptotic member of the Bcl-2 family whose degradation is regulated by Usp9X, causes rapid death in human MPNST cell lines." (PMID 30478285, 2018). "For example, USP9X is a deubiquitinating enzyme overexpressed in malignant nervous system tumors and plays a critical role in MPNST cell survival." (PMID 32848608, 2020).
USP9X also shares sentences with these, for which no sentence is quoted: lupus (2 papers); oral squamous cell carcinoma (2); scoliosis (2); abdominal aortic aneurysm (1); acute myeloid leukaemia (1); anal atresia (1); anaplastic astrocytoma (1); astrocytoma (1); autism spectrum disorder (1); benign tumor (1); Blepharophimosis (1); blood cancers (1); brain malformations (1); breast (1); choanal atresia (1); cleft palate (1); congenital contractural arachnodactyly (1); congenital glaucoma (1); dementia (1); Diffuse Lewy Body Disease (1); Dravet syndrome (1); dyslipidemia (1); dyspraxia (1); endometrial carcinoma (1); facial clefting (1); Freeman-Sheldon syndrome (1); genetic disorders (1); Kabuki syndrome (1); Larsen syndrome (1); lung squamous cell carcinoma (1).
A further 26 diseases each share a sentence with USP9X in 1 paper.